SENP1 (SUMO specific peptidase 1)
Diseases named in the same sentence as SENP1 in open-access papers (continued):
Sharing a sentence is not in itself a finding about the gene and the disease.
acute myeloid leukemia (3 papers, 2024 to 2025). Acute myeloid leukemia (AML) is a group of neoplasms arising from precursor cells committed to the myeloid cell-line differentiation. "SENP1 activates sirtuin 3 (SIRT3) by preventing its proteasome degradation through which exacerbates resistance against chemotherapy in acute myeloid leukemia (AML) cells." (PMID 38389923, 2024).
anemia (3 papers, 2016 to 2022). A reduction in the number of red blood cells, the amount of hemoglobin, and/or the volume of packed red blood cells. "Since SENP1 deficiency in mice leads to embryonic lethality due to massive fetal liver apoptosis and anemia after post-coital day E14.527, we considered the possibility that RIPK1 activation might contribute to the cell death phenotype of SENP1-deficient mice." (PMID 36414671, 2022). "Senp1−/− mice die around E14.5 due to fetal liver cell death, anemia and hypoplasia." (PMID 36414671, 2022).
chronic mountain sickness (3 papers, 2019 to 2024). A pathological condition resulting from chronic exposure to hypoxia at high altitude. "Polymorphisms in SENP1 have been correlated with chronic mountain sickness but not with lipid-related diseases as of yet." (PMID 33154164, 2021).
clear cell renal cell cancer (3 papers, 2016 to 2022). "In the present study, we found that combined high expression of SENP1 and HIF2α (SENP1hi/HIF2αhi) is a poor prognostic marker for patients with clear cell renal cell cancer (ccRCC)." (PMID 36284084, 2022).
cognitive decline (3 papers, 2021 to 2023). "SENP1 overexpression inhibits inflammation caused by intermittent hypoxia, while SENP1 knockout leads to cognitive decline in mice." (PMID 37033632, 2023). "Herein, we investigated the precise mechanism underlying SENP1 and PPARγ in cognitive decline after IH insult." (PMID 34035184, 2021). "So, we investigated the mechanism of IH associated cognitive decline, which revealed that SENP1 played an anti‐inflammatory role in IH‐induced inflammatory response and a protective role in the hippocampus of IH impairment." (PMID 34120412, 2021). "In this study, we aimed to determine whether SENP1 depletion would deteriorate cognitive decline in IH mouse models, and if so, by what mechanism." (PMID 34035184, 2021). "Based on these findings, we hypothesized that SENP1 regulates microglia‐mediated neuroinflammatory response toward IH‐induced cognitive decline through the de‐SUMOylating of NEMO and subsequently inhibiting the activation of NF‐κB." (PMID 34120412, 2021). "Based on these findings, we hypothesize that SENP1 regulates microglia-mediated inflammatory response toward IH-induced cognitive decline through the de-SUMOylation of PPARγ." (PMID 34035184, 2021). "SENP1 depletion aggravated neuroinflammation and neuronal apoptosis via promoting the SUMOylation of PPARγ, reducing the level of PPARγ, thus exaggerating IH-induced cognitive decline." (PMID 34035184, 2021). "Besides, IH induced cognitive decline in mice, and SENP1 deletion aggravated IH‐induced cognitive decline." (PMID 34120412, 2021). "In addition, we also found that IH-induced neuroinflammation led to neuronal apoptosis and neuroinflammation that aggravated by SENP1 depletion promoted the apoptosis, thus contributing to the consequential exaggeration of cognitive decline." (PMID 34035184, 2021). "Overall, the results demonstrated that SENP1 regulated IH‐induced neuroinflammation by modulating the SUMOylation of NEMO, thus activating the NF‐κB pathway, revealing that targeting SENP1 in microglia may represent a novel therapeutic strategy for IH‐induced cognitive decline." (PMID 34120412, 2021).
ischemia (3 papers, 2016 to 2024). A hypoperfusion of the BLOOD through an organ or tissue caused by a PATHOLOGIC CONSTRICTION or obstruction of its BLOOD VESSELS, or an absence of BLOOD CIRCULATION. "Our results reveal an unexpected protective role of neuronal SENP1 in ischemia followed by reperfusion, which should inform new strategies for neuroprotection in ischemic stroke." (PMID 27882949, 2016). "During renal ischaemia, the knockdown model significantly reduced SENP1 expression." (PMID 39205481, 2024). "In addition, SENP1 expression is up‐regulated in ischemia condition, and further supporting the importance of SENP1 in ischemia." (PMID 32495523, 2020).
ischemic stroke (3 papers, 2016 to 2025). A stroke disorder caused by obstruction of blood flow to the brain, due to thrombotic (local blood clot formation) or embolic (due to a blood clot or other material traveling from another site) event. "Verifying the protective role of SENP1 in these neurons will aid the design of new strategies for preventive and therapeutic interventions in clinically relevant pathological states associated with ischemic stroke." (PMID 27882949, 2016). "The dysregulation of SENP1 is closely involved in major neurological diseases, including ischemic stroke and autism spectrum disorder." (PMID 41272902, 2025). "Pericytes‐derived SENP1 may be a potential target for protecting brain from ischemic stroke in future studies." (PMID 32495523, 2020).
liver cancer (3 papers, 2020 to 2024). An epithelial or non-epithelial malignant neoplasm that arises from the liver. "For liver cancer, the expression level of SENP1 is obviously higher in tumor tissues than para-carcinoma tissues." (PMID 38389923, 2024). "Moreover, the association between high expression of UBE2T or simultaneously high expression of UBE2T and SENP1 with lower survival rate was showed by TCGA database and KM plotter liver cancer dataset." (PMID 31969492, 2020). "SENP1 overexpression increases CD24+ cell population and upregulates stemness-related genes expression in liver cancer cells." (PMID 38389923, 2024). "Compared with mouse normal liver tissues, the IHC staining revealed that the levels of SENP1 and RHOU were a relatively high expression in mouse liver cancer tissues, but AnxA6 was decreased." (PMID 38566133, 2024).
lung adenocarcinoma (3 papers, 2021 to 2025). A carcinoma that arises from the lung and is characterized by the presence of malignant glandular epithelial cells. "Overexpression of SENP1 has also been shown to be involved in lung adenocarcinoma progression, and SAE1, UBC9, and SENP3 are remarkably upregulated in lung adenocarcinoma and are associated with poor prognosis." (PMID 37123398, 2023). "Compared to normal lung tissue, lung adenocarcinoma (LUAC) exhibited highly elevated levels of SUMO1 and SENP5, whereas lung squamous cell carcinoma (SCC) showed increased expression of UBC9, SENP1 and SENP5." (PMID 41268439, 2025).
lung fibrosis (3 papers, 2022 to 2023). "Interventions targeting SENP1 can restore the repair function of LR-MSCs with potential therapeutic effect on pulmonary fibrosis." (PMID 35836260, 2022). "The expression of SENP1 increased in LR-MSCs transition of bleomycin (BLM)-induced lung fibrosis." (PMID 35836260, 2022). "In the present study, bronchial installation of Senp1-silenced LR-MSCs could improve the pathology of pulmonary fibrosis in BLM mice." (PMID 35836260, 2022). "Downregulation of SENP1 in LR-MSCs could reverse the transformation of LR-MSCs into myofibroblasts and restore their repair function, thus ameliorating pulmonary fibrosis of the mice BLM model." (PMID 35836260, 2022). "SENP1 might be a potential target to restore the repair function of LR-MSCs and treat pulmonary fibrosis." (PMID 35836260, 2022). "Therefore, we speculated that SENP1 might be a potential target for treating pulmonary fibrosis by preventing the myofibroblast differentiation of LR-MSCs." (PMID 35836260, 2022). "As a result, SENP1 has emerged as a promising therapeutic target for the restoration of LR-MSC physiological functions and the treatment of pulmonary fibrosis." (PMID 37670258, 2023). "Interfering with expression of SENP1 inhibited the transformation of LR-MSCs into myofibroblasts in vitro and in vivo and restored their therapeutic effect in BLM lung fibrosis." (PMID 35836260, 2022).
melanoma (3 papers, 2015 to 2021). A malignant, usually aggressive tumor composed of atypical, neoplastic melanocytes. "Plasma exosome-derived SENP1 levels in melanoma patients were significantly upregulated compared with those in healthy controls (P < 0.001)." (PMID 34422639, 2021). "The AUROC of plasma exosome-derived SENP1 for predicting 3-year OS of melanoma patients was 0.76 (95% CI: 0.67–0.83)." (PMID 34422639, 2021). "First, although this was a large study to evaluate the plasma exosome-derived SENP1 levels in melanoma patients, its prognostic value needs to be verified by multicenter and larger samples." (PMID 34422639, 2021). "The plasma exosome-derived SENP1 levels of melanoma patients and healthy controls were detected with ELISA." (PMID 34422639, 2021). "We showed that plasma exosome-derived SENP1 levels in melanoma patients were significantly upregulated, which is consistent with the trend in SENP1 protein expression in melanoma patients." (PMID 34422639, 2021). "We also investigated the correlations between plasma exosome-derived SENP1 levels and tumor characteristics in melanoma patients." (PMID 34422639, 2021). "Plasma exosome-derived SENP1 levels in melanoma patients were significantly upregulated than in healthy controls (P < 0.001)." (PMID 34422639, 2021). "Second, the mechanism of plasma exosome-derived SENP1 affecting the prognosis of melanoma patients needs to be studied in vivo and in vitro." (PMID 34422639, 2021). "In summary, our study demonstrated that melanoma patients with higher plasma exosome-derived SENP1 levels had worse DFS and OS." (PMID 34422639, 2021). "Disease-free survival (DFS) and overall survival (OS) were worse in melanoma patients who had higher plasma exosome-derived SENP1 levels than lower plasma exosome-derived SENP1 levels (both P < 0.001)." (PMID 34422639, 2021). "The AUROC of plasma exosome-derived SENP1 for predicting 3-year OS of melanoma patients was 0.76 (95% CI: 0.67–0.83), with a sensitivity of 95.7% (95% CI: 85.5–99.5%) and specificity of 62.0% (95% CI: 50.4–72.7%)." (PMID 34422639, 2021). "And also, we determined the expression of SENP1 in the tissues of melanoma patients by IHC, and found that the SENP1 protein level was significantly higher than that in the adjacent tissues, but its relationship with the prognosis of patients was not obvious." (PMID 34422639, 2021). "In this study, we aimed to investigate plasma exosome-derived SENP1 levels and determine their prognostic value in melanoma patients." (PMID 34422639, 2021). "In addition, Kaplan-Meier analysis showed that both DFS and OS were worse in melanoma patients who had higher plasma exosome-derived SENP1 levels than in those with lower plasma exosome-derived SENP1 levels (both P < 0.001)." (PMID 34422639, 2021). "In addition, both DFS and OS were worse in melanoma patients who had higher plasma exosome-derived SENP1 levels than in those with lower plasma exosome-derived SENP1 levels." (PMID 34422639, 2021). "The prognostic value of plasma exosome-derived SENP1 in melanoma patients." (PMID 34422639, 2021). "We compared the plasma exosome-derived SENP1 levels between melanoma patients and healthy controls." (PMID 34422639, 2021). "Melanoma patients with higher plasma exosome-derived SENP1 levels had worse DFS and OS." (PMID 34422639, 2021). "Hence, we aimed to investigate plasma exosome-derived SENP1 levels and determine their prognostic value in melanoma patients in this study, which is believed to be the first to assess the potential of plasma exosome-derived SENP1 in melanoma diagnosis." (PMID 34422639, 2021). "We showed that plasma exosome-derived SENP1 had good performance for predicting 3-year DFS and 3-year OS of melanoma patients." (PMID 34422639, 2021). "We assessed the value of plasma exosome-derived SENP1 for predicting 3-year DFS and OS of melanoma patients with ROC curve analysis." (PMID 34422639, 2021).
melanoma (continued). "However, the expression and prognostic value of SENP1 in melanoma patients remain unclear." (PMID 34422639, 2021). "The plasma exosome-derived SENP1 levels may be a potential prognostic predictor for 3-year DFS and OS of melanoma patients." (PMID 34422639, 2021). "The plasma exosome-derived SENP1 levels may be a potential prognostic predictor for 3-year DFS and 3-year OS of melanoma." (PMID 34422639, 2021).
myocardial ischemia (3 papers, 2019 to 2025). A disorder of cardiac function caused by insufficient blood flow to the muscle tissue of the heart. "To investigate the impact of SENP1 in myocardial ischemia in vivo, we generated cardiac muscle tissue‐specific SENP1 knockdown (SENP1‐TKO) mice by crossing Myh6‐MerCreMer mice with SENP1fl/fl mice." (PMID 40341856, 2025). "SENP1 was initially thought to protect against myocardial ischemia/reperfusion injury." (PMID 38225750, 2024). "Indeed, SENP1, SENP2 and SENP5, as well as SENP3, have each been strongly implicated in cardiac ischemia/reperfusion so it is likely that distinct subsets of SUMOylated proteins are regulated by different SENPs." (PMID 30973885, 2019).
non-small cell lung carcinoma (3 papers, 2021). A group of at least three distinct histological types of lung cancer, including non-small cell squamous cell carcinoma, adenocarcinoma, and large cell carcinoma. "Small ubiquitin-like modifier-specific protease 1 (SENP1) plays vital roles in cancer progression and chemoresistance, but its prognostic value in non-small cell lung cancer (NSCLC) is vague." (PMID 35782332, 2021).
Stroke (3 papers, 2016 to 2025). Sudden impairment of blood flow to a part of the brain due to occlusion or rupture of an artery to the brain. "Our findings revealed that targeting SENP1 in pericytes may represent a novel therapeutic strategy for neurovascular protection in stroke." (PMID 32495523, 2020). "Since DAPK1 is also dysregulated in various brain disorders such as stroke and AD, and because DAPK1 and SENP1 directly bind, we wondered whether DAPK1 can affect SENP1 function." (PMID 41272902, 2025).
atherosclerosis (2 papers, 2022). A disease characterized by the build-up of fatty material and calcium deposition in the arterial wall resulting in partial or complete occlusion of the arterial lumen. "Endou, Hdac7, Senp1, Olfr286, Olfr285, Nckap5l, Smarcd1, Lima1, Fam186a, and Espl1 are probable candidate genes for distal Chr15 atherosclerosis QTL (Ath53)." (PMID 36078077, 2022). "SENP1 modulates the SUMOylation of GATA2 and leads to endothelial dysfunction in graft atherosclerosis." (PMID 36293488, 2022).
bladder cancer (2 papers, 2010 to 2023). "We could use the urinary content of hTERT, SENP1, PPP1CA, and MCM5 to detect bladder cancer recurrence." (PMID 21106093, 2010).
cardiac failure (2 papers, 2024 to 2025). "Additionally, we assessed the therapeutic potential of adeno‐associated virus 9 (AAV9)‐mediated Senp1 gene delivery in improving cardiac pathology and reversing postischemic heart failure in a preclinical model of heart failure." (PMID 40341856, 2025). "Our results provided strong evidence that SENP1 attenuates pathological cardiac failure in the mouse ICM model and improves left ventricular (LV) function." (PMID 40341856, 2025). "Here, the authors show that sentrin-specific protease 1 (SENP1) is downregulated in post-MI mice and in patients with severe heart failure." (PMID 38992961, 2024).
Cognitive impairment (2 papers, 2021 to 2025). Abnormal cognition is characterized by deficits in thinking, reasoning, or remembering. "SENP1-mediated deSUMOylation of nuclear factor κB essential modulator, β-catenin, peroxisome proliferator-activated receptor γ, and the target of Myb1 in microglia antagonizes the inflammatory response and cognitive impairment induced by IH." (PMID 41272902, 2025).
diabetes (2 papers, 2015 to 2016). "Our results indicated that prophylactic insulin therapy in SENP1-deficient mice at the age of 5 weeks for 9 weeks only partially ameliorates development of diabetes phenotypes including immune cell infiltration, β-cell apoptosis and islet disruptions." (PMID 26596471, 2015). "All SENP1-deficient mice had lower body weights compared with the control mice after onset of diabetes." (PMID 26596471, 2015). "Our data demonstrate that T1DM onset in the SENP1-deficient mice is strongly associated with high levels of proinflammatory cytokines secreted by PATs, underlying a mechanistic link between peri-pancreatic adipocytes and diabetes." (PMID 26596471, 2015). "Subsequently, the cytokines and activated immune cells, especially CD8+ and CD4+T cells, attack the pancreases, leading to the chronic destruction of the islet structures, damaged β cells, autoantibody onset and diabetes progression in the SENP1-deficient mice." (PMID 26596471, 2015). "To determine the pathogenesis of diabetes in SENP1-deficient mice, we examined pancreatic development and pathology by haematoxylin and eosin stain and immunostaining for pancreatic β-cell number, mass and morphology changes, as well as immune cell invasion, indicative of insulitis." (PMID 26596471, 2015). "Previously, the SENP1-mediated protein sumoylation has been demonstrated to play a key role in pancreatic immune responses, β-cell damage, and, consequently, diabetes progression." (PMID 27110392, 2016). "Here we show that mice with a adipocyte-specific deletion of the SUMO-specific protease SENP1 gene develop symptoms of type-1 diabetes mellitus (T1DM), including hyperglycaemia and glucose intolerance with mild insulin resistance." (PMID 26596471, 2015). "In summary, our experiments define the role of the SENP1-mediated protein SUMOylation in pancreatic immune responses, β-cell damages and consequently diabetes progression." (PMID 26596471, 2015). "Taken together, our results support that SENP1-aP2KO mice is a clinically relevant model for human diabetes." (PMID 26596471, 2015). "We found that the circulating proinflammatory cytokines IL-6, TNF-α and IL-Iβ, but not IFN-γ, were significantly elevated in the SENP1-deficient mice before the onset of diabetes at the age of 7 weeks." (PMID 26596471, 2015). "SENP1 has been shown to be a molecular mechanism for the pathogenesis of diabetes, and it may help to develop a novel therapeutic strategy for the treatment of diabetes." (PMID 27110392, 2016). "Our data support that SENP1-mediated NEMO deSUMOylation in the peri-pancreatic adipocytes limits inflammatory responses and diabetes progression." (PMID 26596471, 2015). "PATs from SENP1-aP2KO mice expressed high levels of IL-6, TNF-α and IL-1β at the age of 7 weeks before the onset of diabetes, and these proinflammatory cytokines were higher in the PATs compared with other adipose depots." (PMID 26596471, 2015).
endometrial cancer (2 papers, 2022 to 2025). Primary or metastatic malignant neoplasm involving the endometrium (mucous membrane that lines the endometrial cavity). "SENP1deletion increases ER-α SUMOylation resulting in endometrial hyperplasia or endometrial cancer as shown in mice with a stromal SM22α-specific SENP1 deletion (SENP1 smKO)." (PMID 36612107, 2022).
endothelial dysfunction (2 papers, 2017 to 2022). In vascular diseases, endothelial dysfunction is a systemic pathological state of the endothelium (the inner lining of blood vessels) and can be broadly defined as an imbalance between vasodilating and vasoconstricting substances produced by (or acting on) the endothelium. "Indeed, the clinical observation was supported by remarkably attenuated leukocyte infiltration and neointima expansion as well as endothelial dysfunction in SENP1-ecKO murine allografts." (PMID 28569748, 2017). "Therefore, upon inflammation, endothelial SENP1-mediated SUMOylation drives GA by regulating the synergistic effect of GATA2 and NF-κB and consequent endothelial dysfunction." (PMID 28569748, 2017).